TNF (tumor necrosis factor)
Diseases named in the same sentence as TNF in open-access papers (continued):
Sharing a sentence is not in itself a finding about the gene and the disease.
brain inflammation (continued). "On the other hand, GSK-3β also functions as a negative regulator of pro-inflammatory cytokine expression and decreased GSK-3β expression may render Pink1−/− mice more vulnerable to TNF-α, IL-1β and LPS-induced brain inflammation." (PMID 21249202, 2011). "Additionally, AD is marked by brain inflammation, evidenced by heightened activity in the astrocytes and microglia, along with elevated levels of proinflammatory cytokines such as interleukin-1β, interleukin-6, and tumor necrosis factor-α." (PMID 39932627, 2025). "Indeed, although limited, data in literature indicate that in both acute (i.e., ICV injection of cytokine) and chronic (i.e., EAE and AD transgenic model) paradigms of brain inflammation, IL-1β is still linked to LTP expression, whereas TNF seems to affect both LTP and synaptic scaling." (PMID 29861718, 2018). "Given the link between gut dysbiosis and brain inflammation via the gut-brain axis, we examined key pro-inflammatory markers, including TLR4, TNF-a, and IL-1B." (PMID 41286043, 2025). "Our findings revealed that the serum levels of IL-4, IFN-α, IFN-γ, IL-6, TNF-α, CCL4, P-cadherin, TRAIL, CCL11, and VEGF were significantly higher in cases of brain inflammation compared with brain gliomas." (PMID 39364412, 2024). "In conclusion, HFD feeding induces an array of inflammatory cytokines including TNF-α and IFN-γ which in turn promotes neuron cell death and brain inflammation." (PMID 35154484, 2022). "Our results suggest that DOX and MLX exert neuroprotective effects by decreasing proinflammatory cytokine (TNF-α, IL-6 and IL-17) levels and COX-2 synthesis in brain inflammation." (PMID 33149866, 2020). "Brain inflammation often involves expression of IL-1β, IL-6, IL-8, TGF-β1, and TNF-α, thus we started our screening experiments with these commercially available inflammatory factors." (PMID 33013631, 2020). "Glial cell and EC responses during infection indicate that soluble molecules, cytokines, and chemokines such as RANTES, TNF-α, IL-6, IL-10, and MCP-1 among others, favor leukocyte infiltration, worsening brain inflammation." (PMID 31293558, 2019). "Rat BMCs can produce tumor necrosis factor (TNF) and TNF take part in both brain inflammation and increased vascular permeability." (PMID 25944979, 2015). "The excessive production of LPS by the gut microbiota triggers the production of inflammatory cytokines such as IL-6, IL-1β, and TNF-α, further disrupting the HPA axis, increasing brain inflammation, and promoting neurodegeneration, which impairs hippocampal neurogenesis." (PMID 40077516, 2025). "ROC analysis of immunological molecules in serum and CSF showed that the expression levels of IL-4, IFN-α, IFN-γ, IL-6, TNF-α, CCL4, CCL11, and VEGF exhibited high sensitivity and specificity in distinguishing between brain inflammation and brain tumor groups (p < 0.05)." (PMID 39364412, 2024). "ELISA data demonstrated that siATP11A significantly increased the expression of IL-6 and TNF-α, while ATP11A overexpression significantly reduced the expression levels of IL-6 and TNF-α, indicating that ATP11A overexpression may alleviate brain inflammation." (PMID 39664587, 2024). "In addition, immunoreactivity for TNF-α was increased in the cortices of PFF-injected animals, suggesting that intravitreal injection of PFF leads to brain inflammation." (PMID 37210559, 2023). "Administration of icariin (30, 60, 120 mg/kg/day) for 17 consecutive days increased spatial learning and memory and reduced tumor necrosis factor-α (TNF-α), interleukin-1(IL1) and cyclooxygenase-2 (COX-2) expression in a rat model with brain inflammation induced by lipopolysaccharide (LPS)." (PMID 31816602, 2019). "Consistent with the results of in vitro experiments, an LPS-induced brain inflammation mouse model, administration of TEC effectively decrease the levels of malondialdehyde, iNOS in hippocampus, and prevented increases in the levels of TNF-α and IL-6 in the serum." (PMID 29867470, 2018).
brain inflammation (continued). "Peripheral surgery may disrupt the BBB via complement activation and pro-inflammatory cytokines, such as TNF-α and high mobility group box-1 (HMGB1), which promotes brain inflammation." (PMID 30501622, 2018). "Therefore, IP-administered etanercept did not reduce the TNF-α and ADMA levels in the plasma significantly, yet it might affect the routes connected with the brain and decrease brain inflammation to a significant extent." (PMID 27445694, 2016).
sarcoma (82 papers, 1995 to 2025). A usually aggressive malignant neoplasm of the soft tissue or bone. "The pro-inflammatory cytokine TNF-α has originally been linked to necrosis in chemically induced sarcomas in mice and later with an ability to cause apoptosis of tumor cells through TNFR1." (PMID 37232720, 2023). "We observed stress-associated pathways in each sarcoma type that was enriched in the Warm protocol, including Hypoxia, Apoptosis, DNA repair, and TNF-alpha Signaling via NF-kB, which is consistent with prior work." (PMID 37254069, 2023). "As its name suggests, TNF-α was originally identified in 1975 as an anticancer agent that causes endotoxin-induced hemorrhagic necrosis in sarcoma and other tumors, and human TNF-α was cloned in 1984." (PMID 35954156, 2022). "TNF-α combined with melphalan has become the standard treatment for advanced limb sarcoma with a good benefit/risk ratio and a remarkable response rate in human patients with heavily pre-treated disease." (PMID 22719951, 2012). "The systemic treatment of mice with SA1 sarcoma with high doses of TNF was reliable at causing a tumor-hemorrhagic reaction that resulted in the destruction of greater than 75% of the tumor’s center in 24 h with the development of numerous hemorrhages in the tumor’s vascular bed." (PMID 36358688, 2022). "And the risk score of PLCG1 and TNF could potentially serve as prognosis markers for sarcoma patients, in clinic." (PMID 34904022, 2021). "Importantly, TNF/Mel/SM treatment caused an increase in immune infiltration of BN175 sarcoma, leading to elevated levels of T cells and natural killer (NK) cells." (PMID 32419365, 2020). "Isolated limb perfusion with TNF-α and melphalan has shown promising results in locally advanced sarcomas, offering an alternative to radiotherapy by improving surgical margins and preserving limb function." (PMID 41458266, 2025). "The regulation of immune response in sarcoma patients was also determined through the measurement of several cytokines including TNF produced by Con-A-stimulated T cells." (PMID 38338920, 2024). "The level of TNF from Con-A-stimulated blood lymphocytes of sarcoma patients was found to be reduced compared to the controls." (PMID 38338920, 2024). "The antitumor effect of high concentrations of TNF-α was observed in a murine sarcoma model, whereas low levels of TNF-α led to a protumorigenic phenotype." (PMID 38520006, 2024). "A pilot study reported a remarkable decrease in the number of CD4+ T-cells (p = 0.037) and the level of TNF (p = 0.004) in sarcoma patients." (PMID 38338920, 2024). "Further research has demonstrated that TNF knockout mice were more susceptible to skin sarcoma induced by 3′-methylcholanthrene (MCA) compared to wild-type mice, indicating that TNF provides protection against MCA-induced sarcoma formation." (PMID 39605908, 2024). "After stimulation with TNF-α (1.0 ng/mL), quantitative real-time PCR of sarcoma osteogenic (SaOS-2) cells revealed that 6A-8R (1.5 and 3.0 mg/mL) inhibited the expression of the sclerosteosis gene (SOST)." (PMID 37991021, 2023). "Tumor necrosis factor alpha (TNF-α) was discovered back in 1975 as a factor released from host cells, causing hemorrhagic necrosis of sarcoma Meth A and other tumors." (PMID 36839658, 2023). "This was confirmed in a mouse model of Meth A sarcomas that showed strong hemorrhagic necrosis after an intralesional injection with TNF." (PMID 36358688, 2022). "There were reduced levels (p < 0.05) of IFN -γ and TNF-α from Con-A-stimulated peripheral blood lymphocytes from sarcoma patients compared to normal controls." (PMID 36005179, 2022). "Our study showed reduced CD4+ T cells, IFN-γ, and TNF-α and identification of peripheral immune related genes in sarcoma patients compared to healthy controls, indicating reduced anti-cancer immunity in these patients." (PMID 36005179, 2022).
sarcoma (continued). "TNF (Beromun®) is administered locally for the treatment of sarcoma patients by means of isolated limb perfusion procedures at 2–2.5 mg/m2." (PMID 34576184, 2021). "A TNF immunocytokine specific for EDB reiterated these results by increasing the cure rate for dacarbazine and trabectedin in a syngeneic sarcoma model with a temporary acute loss of body weight." (PMID 33803078, 2021). "Tumor necrosis factor (TNF) has been approved for clinical use in Europe for isolated limb perfusions of sarcoma patients in conjunction with the chemotherapeutic agent melphalan." (PMID 33803078, 2021). "Approximately 80% of tumor eradication was seen in colon cancer and sarcoma models when anti-PD-L1 was co-administered with IL-2 or TNF and IL-2 immunocytokines targeted to EDA and EDB." (PMID 33803078, 2021). "Targeting a trimeric TNF to EDA led to cures in two different sarcoma models when given in conjunction with doxorubicin at a concentration insufficient to cause tumor regression alone." (PMID 33803078, 2021). "On the other hand, the higher the expression levels of TNF, the higher the possibility of survival in sarcoma patients; the TNF gene had a positive correlation with patient survival in sarcoma." (PMID 34904022, 2021). "Hallahan and colleagues reported that treatment of human sarcoma cells with ionizing radiation led to an increase in TNF mRNA and an increased production of TNF protein." (PMID 32053868, 2020). "To test whether this was due to the development of resistance to the TNF/Mel/SM treatment or was caused by attaining a transient state called “persistence” without mutation, we isolated drug‐tolerant tumour cells from three rats (124, 133 and 136) that developed sarcomas post‐treatment." (PMID 32419365, 2020). "On the other hand, TNF-α was shown to increase human OS cells′ susceptibility to NK lysis by CD54 and CD58 upregulation, demonstrating a dual role of TNF-α in NK-sarcoma interactions." (PMID 33322371, 2020). "Together, these data suggest that the addition of SM to the ILP standard‐of‐care TNF/Mel treatment activates the immune system to BN175 sarcoma, leading to activation of infiltrating T cells." (PMID 32419365, 2020). "TNF-α, also known as TNF, was first identified as a tumoricidal protein that mediates endotoxin-induced hemorrhagic necrosis in sarcoma and other transplanted tumors in 1975." (PMID 31816903, 2019). "Identified in 1975 and cloned in 1984, TNF was named regarding its capacity to induce the necrosis of transplanted methylcholanthrene-induced sarcomas in mice, when injected at a high concentration in tumors." (PMID 31417576, 2019). "For example, at high concentrations, TNFα can kill sarcoma cells by binding to the TNFR1 and inducing apoptosis." (PMID 28424760, 2017). "LiCl induced apoptotic cell death in human sarcoma and carcinoma cell lines was accompanied by TNF-α and FasL expression inducing PARP and caspase 3, 8 and 10 cleavage." (PMID 28575066, 2017). "A sublethal dose of BV6 significantly increased the sensitivity of human sarcoma cells to TNFα-induced cell death." (PMID 27014915, 2016). "For this purpose, sarcoma tumours (n = 8) treated ex vivo with TNF-α were processed for TUNEL staining." (PMID 22719951, 2012). "Isolated limb perfusion with TNF-α and melphalan is used with remarkable efficiency to treat unresectable limb sarcomas." (PMID 22719951, 2012). "The tumor necrosis factor (TNF, TNF-α) was originally characterized as a necrosis inductor in sarcomas in vivo." (PMID 23251798, 2012).
sarcoma (continued). "For example, tumor necrosis factor-alpha (TNF-α) was produced by human sarcoma cells exposed to a single dose of 5 Gy." (PMID 23112958, 2012). "In spite of the indicated usefulness of doxorubicin in ILP for the treatment of sarcoma, we and others observed dose-limiting local toxicity after a TNF-based ILP with conventional doxorubicin." (PMID 15208623, 2004). "In both tumour models increased accumulation of doxorubicin in tumour tissue was found: 3.1-fold in the BN175 and 1.8-fold in the ROS-1 sarcoma after ILP with doxorubicin combined with TNF-α in comparison with an ILP with doxorubicin alone." (PMID 10732774, 2000). "We have shown previously that isolated limb perfusion (ILP) in sarcoma-bearing rats results in high response rates when melphalan is used in combination with tumour necrosis factor alpha (TNF-α)." (PMID 10732774, 2000). "Here we show that ILP with doxorubicin in combination with TNF-α has comparable effects in two different rat sarcoma tumour models." (PMID 10732774, 2000). "The enhanced level of SQLE and the reduced levels of TNF observed in sarcoma patients in this study indicate that the synergistic effects of both factors may support tumor angiogenesis and progression." (PMID 38338920, 2024). "The expressions of SQLE and TNF in sarcoma demonstrated the opposite prognostic prediction." (PMID 38338920, 2024). "Importantly, when gated on CD69+CD49a+ or CD69+CD103+ cells, DFMO cotreatment led to increased levels of IFN-γ and TNF-α in post–rapid expansion protocol (post-REP) human sarcoma TIL." (PMID 37581943, 2023). "After sarcoma surgery, blood vessels of the treated limb are being reconnected to form a closed system with a pump and treated with extremely high concentrations of melphalan, TNF-α, and mild hyperthermia." (PMID 33322371, 2020). "Using a rat model of aggressive extremity sarcoma, we demonstrate that TNF‐mediated cell death significantly improves local disease control, increases activation of infiltrating CD8+ T cells and NK cells, and enhances the survival benefit of immune checkpoint blockade." (PMID 32419365, 2020). "Induction chemotherapy by ILP using melphalan with recombinant human tumour necrosis factor alpha (TNFα) prior to a limb-conserving surgical resection was introduced as a strategy for locally advanced sarcomas considered irresectable other than by an amputation." (PMID 29988594, 2018). "In a sarcoma mouse model, it has been shown that the pretreatment with sublethal TNF doses may not only prevent the toxic effects of lethal doses of TNF but also reduce its antitumour effects, even when further increased doses were applied in tolerant mice." (PMID 29250561, 2017). "Because elevated TNF-α expression was observed in sarcoma tumors, we hypothesized that another potential mechanism for Notch activation could be TNF-α released by the tumor into the systemic circulation exerting an effect on skeletal muscle." (PMID 27378829, 2016). "Hence, the aim of the present study was to explore the possibility of adjuvant tumour necrosis factor α (TNF-α) therapy to potentiate antitumor effectiveness of electrochemotherapy with intravenous cisplatin administration in murine sarcoma." (PMID 25810699, 2015). "Therefore, the aim of the present study was to explore the possibility of adjuvant intratumoural TNF-α therapy to electrochemotherapy with intravenous CDDP administration in murine sarcoma." (PMID 25810699, 2015). "Similarly, neutralizing endogenous TNFα/cachectin production with antibodies reduced tissue wasting and tumor weights of methylcholanthrene-induced sarcoma (MCG-101), as well as Lewis lung carcinoma." (PMID 24787299, 2014).